MUC3A (mucin 3A, cell surface associated)
Diseases named in the same sentence as MUC3A in open-access papers (continued):
Sharing a sentence is not in itself a finding about the gene and the disease.
cancer (12 papers, 2016 to 2025). A tumor composed of atypical neoplastic, often pleomorphic cells that invade other tissues. "The methylation status of MUC3A is also utilized as an epigenetic diagnostic marker for carcinogenic risk and prognosis in cancer patients." (PMID 35038288, 2022). "In previous studies, overexpression of MUC3A in different types of cancers showed a close association with metastasis and poor prognosis." (PMID 35655161, 2022). "MUC3A is a membrane-associated mucin that recent evidence reveals the role of MUC3A in pathogenesis and progression of cancers." (PMID 27374181, 2016). "MUC3A is a membrane-associated MUC with abnormal expression in various cancers and may involve in tumorigenesis and progression." (PMID 34326691, 2021). "MUC3A is a membrane-associated mucin that is involved in cancer pathogenesis and progression." (PMID 30106962, 2018). "As similar to MUC1 and MUC16, MUC3A is also a membrane-associated mucin and maybe applied in serodiagnostic tests to diagnosis and monitor cancers." (PMID 27374181, 2016). "Tissue microarray containing 92 LUAD and paired para-carcinoma tissues with scoring system was used to confirm the increased MUC3A and PD-L1 levels in LUAD tissues compared with normal lung tissues." (PMID 33994852, 2021). "Consistent with other cancers types according to former studies, high MUC3A expression was identified as an adverse independent prognosticator for OS and RFS in localized ccRCC following surgery." (PMID 27374181, 2016). "MUC3A plays a role in the pathogenesis and progression of cancers." (PMID 35038288, 2022). "Additionally, DNA hypomethylation was illustrated to perform an instrumental function in MUC3A expression in carcinomas." (PMID 36059804, 2022). "Besides its meaningful prognostic value, the prospect of MUC3A in cancer diagnosis and treatment has also been paid more and more attention these years." (PMID 27374181, 2016). "In addition, hypomethylation contributes to the expression of MUC3A in cancer cells." (PMID 35038288, 2022). "The mechanism of MUC3A upregulation in cancers remains unclear." (PMID 34326691, 2021). "By determining expressions of the three MUCs in additional 68 pairs of samples, we confirmed the upregulations of MUC5AC and MUC5B but not MUC3A in cancer tissues." (PMID 37324942, 2023). "Our findings suggest that MUC3A may contribute to OGCT development, although little is known about the functional role of MUC3A in cancer pathology." (PMID 35038288, 2022). "Surprisingly, patients with MUC3A, MUC4, MUC5B, MUC6, and MUC16 mutations had significantly better OS prognoses compared with those without mutations in several cancer types." (PMID 30107644, 2018). "In addition, MUC3A expression may regulated by PKC signal pathway and therefore modulated the invasive and metastatic properties in cancer cells." (PMID 27374181, 2016).
adenocarcinoma (2 papers, 2020 to 2021). A common cancer characterized by the presence of malignant glandular cells. "Adenocarcinoma with higher levels of MUC3A (IHC > 140) also had higher expression of PD-L1 than the lower ones (p < 0.05)." (PMID 33994852, 2021).
MUC3A also shares sentences with these, for which no sentence is quoted: breast carcinoma (3 papers); infection (3); Obesity (3); acute myeloid leukaemia (1); ccRcc (1); chronic myeloid leukemia (1); chronic obstructive airway disease (1); esophageal adenocarcinoma (1); gastric adenocarcinoma (1); gastric cancer (1); gastroesophageal junction adenocarcinoma (1); genitourinary cancers (1); glioma (1); Huntington disease (1); kidney disease (1); lung adenocarcinoma (1); lung squamous cell carcinoma (1); malakoplakia (1); meningioma (1); mucinous colorectal adenocarcinoma (1); ovarian carcinoma (1); pancreatic cancer (1); rectal adenocarcinoma (1); Wilms tumor (1).